MUC2 (mucin 2, oligomeric mucus/gel-forming)
Diseases named in the same sentence as MUC2 in open-access papers (continued):
Sharing a sentence is not in itself a finding about the gene and the disease.
Lynch syndrome (1 paper, 2017). An autosomal dominant hereditary neoplastic syndrome characterized by the development of colorectal carcinoma and a high risk of developing endometrial carcinoma, gastric carcinoma, ovarian carcinoma, renal pelvis carcinoma, and small intestinal carcinoma. "Differences were identified for CK20 and nuclear β-catenin, which were significantly more often expressed in FCCTX than in Lynch syndrome (p < 0.001), whereas MUC2, MUC5AC and MUC6 were overexpressed in Lynch syndrome tumors compared with FCCTX tumors (p = 0.001, < 0.01, and < 0.001, respectively)." (PMID 28824332, 2017). "Tumors linked to Lynch syndrome and FCCTX showed significant differences, primarily related to frequent expression of CK20 and nuclear β-catenin in FCCTX and relative over-expression of MUC2, MUC5AC and MUC6 in Lynch syndrome." (PMID 28824332, 2017). "We compared the expression patterns of cytokeratins (CK7 and CK20), mucins (MUC2/5 AC/6), CDX2 and β-catenin in Lynch syndrome and FCCTX." (PMID 28824332, 2017). "Our study on the secreted gel-forming mucins (MUC2, MUC5AC, and MUC6) demonstrated significantly higher values in the Lynch syndrome than in the FCCTX tumors." (PMID 28824332, 2017).
malnutrition (1 paper, 2021). Inadequate nutrition resulting from poor diet, malabsorption, or abnormal nutrient distribution. "A previous study found that the defense protein MUC2−/− mice were suffering from malnutrition at 4 weeks old, and the abundance of the microbial community was more complicated than that of normal mice." (PMID 33954162, 2021).
mental disorder (1 paper, 2024). A disease that has its basis in the disruption of mental process. "Alterations in MUC2 function can lead to increased intestinal permeability, which has been implicated in systemic inflammation, a factor associated with severe mental disorders through the gut–brain axis and the onset of cardiovascular diseases." (PMID 39457610, 2024).
metastasis (1 paper, 2005). The spread or migration of cancer cells from one part of the body (where they first appeared) to another. "Nearby are the MUC2 and MUC6 genes (11p15) that might be related to lymph node metastasis." (PMID 15870709, 2005).
microcephaly (1 paper, 2022). A congenital or acquired developmental disorder in which the circumference of the head is smaller than normal for the person's age and sex. "To study the effect on anterior head structure formation and to determine whether the embryos exhibit normal, mild, or severe microcephaly, we analyzed the development of the eyes (pax6) and cement gland (muc2) by in situ hybridization." (PMID 35372345, 2022).
middle ear infection (1 paper, 2014). "Although, we and others showed the relationship between bacterial infection and overexpression of MUC2 and MUC5AC in the intestine, respiratory tract and middle ear infection but the transcription factor involved in the mucin gene induction was not determined during S. dysenteriae infection." (PMID 25365201, 2014).
mucinous adenocarcinoma of the appendix (1 paper, 2016). Mucinous adenocarcinoma of the appendix is a very rare, slow growing, well-differentiated epithelial neoplasm of the appendix characterized by abundant mucin production. "While the molecular mechanisms of mucinous adenocarcinomas of the appendix remain poorly understood, previous studies have shown positive reactivity for CK20, CDX2 and MUC2 in these tumours." (PMID 27982068, 2016).
Neoplasm of the pancreas (1 paper, 2014). A tumor (abnormal growth of tissue) of the pancreas. "Our previous studies showed that MUC2 expression is related to a good prognosis in neoplasms of the pancreas, bile duct and stomach." (PMID 24722639, 2014).
obstructive jaundice (1 paper, 2018). A finding indicating increased bilirubin levels in the blood and urine, due to intrahepatic or extrahepatic obstruction of the biliary system. "Our animal studies indicated that goblet cells and MUC2 were reduced in rats with obstructive jaundice, internal biliary drainage, and external biliary drainage increased goblet cells and MUC2." (PMID 29599128, 2018). "A possible mechanism of intestinal mucosa damage in patients with obstructive jaundice is the decrease in MUC2 and goblet cells." (PMID 29599128, 2018). "The present study was to investigate the role of goblet cells and MUC2 in obstructive jaundice and evaluate the effect of biliary drainage on intestinal permeability." (PMID 29599128, 2018).
otitis media (1 paper, 2011). Inflammation of the anatomical structures of the middle ear, which is most often caused by an infectious process. "Interestingly, in rats whose ears were inoculated with Streptococcus pneumoniae, one of the most common pathogens in otitis media, scn1b, muc2 and muc5 were among the genes upregulated, although polymorphisms of SCN1B do not appear to have been investigated in COME/ROM previously." (PMID 21857919, 2011).
Paget disease (1 paper, 2024). A malignant neoplasm composed of large cells with large nuclei, prominent nucleoli, and abundant pale cytoplasm (Paget cells). "Their study demonstrated the use of staining patterns of CK7, GCDFP‐15, CK20, MUC2, and CDX2 to help distinguish Paget's disease from anorectal adenocarcinoma." (PMID 39253370, 2024).
pancreatic disease (1 paper, 2014). "A predictive model for identification of pancreatic disease was constructed using the U-indexes of MUC1, MUC2 and MUC4 based on quadratic or canonical discriminant analysis." (PMID 24714692, 2014).
papillary adenocarcinoma (1 paper, 2025). A morphologic variant of adenocarcinoma. "The mixed gastric-intestinal type intramucosal papillary adenocarcinoma displayed immunopositivity for MUC2, villin, and CDX2, consistent with features of intestinal differentiation." (PMID 41404072, 2025).
prostate tumour (1 paper, 2004). "Overall, MUC2, MUC5B and MUC6 were associated with mucinous morphology, and were expressed in HID prostate tumour variants." (PMID 14760390, 2004). "Using PAC120, a xenograft of a human hormone-dependent prostate tumour, and its hormone-independent variants, we analysed the expression of mucins (MUC1, MUC2, MUC4, MUC5AC, MUC5B, MUC6) by immunohistochemistry or reverse transcriptase (RT)–PCR." (PMID 14760390, 2004).
psoriasis (1 paper, 2023). An autoimmune condition characterized by red, well-delineated plaques with silvery scales that are usually on the extensor surfaces and scalp. "Mice with severe psoriasis-like phenotype showed high mRNA expression of Muc-2 in the colon as well as increased numbers of mucus-secreting goblet cells suggesting the reason for the changes in intestinal microbiota." (PMID 36710269, 2023).
pterygium (1 paper, 2021). A wedge-shaped fibrovascular lesion arising from the bulbar conjunctiva and extending to the cornea. "MUC2 expression was down-regulated in pterygium and pinguecula." (PMID 34769520, 2021). "MUC2 expression was down-regulated in both pterygium subtypes." (PMID 34769520, 2021).
pyloric gland adenoma (1 paper, 2012). A rare neoplastic polyp that arises from the stomach. "The pyloric gland adenoma showed focal positive staining for MUC1, and negative staining for MUC2, as well as superficial staining for MUC5AC, and positive expression of MUC6 and VEGF." (PMID 23206236, 2012). "These tumours did not arise from pyloric gland adenomas, but displayed a similar immunophenotype with positive expression of MUC5AC and MUC6 and negativity for MUC2 and CDX2." (PMID 23206236, 2012).
rhinosinusitis (1 paper, 2015). "Here, we could demonstrate a 1,8-cineol-dependent reduction of mucus-production and particularly MUC19 and MUC2 gene expression in ex vivo cultured human nasal slices in a novel model for experimental rhinosinusitis." (PMID 26207629, 2015).
shigellosis (1 paper, 2011). Shigellosis is a bacterial infection leading to dysentery and is caused by Shigella, which are small, ubiquitous Gram-negative bacteria belonging to the enterobacteria family. "Hence, it was of interest to investigate the relationship between host (mucin) and pathogen interaction, including Shigella induced expression of MUC2 and IL-1β during shigellosis." (PMID 22073249, 2011). "Furthermore, to evaluate the involvement of inflammatory cytokines in the hyper production of MUC2 during shigellosis." (PMID 22073249, 2011).
Sleep apnea (1 paper, 2017). An intermittent cessation of airflow at the mouth and nose during sleep is known as sleep apnea. "Of the six significantly associated variants, two could be tested for association with symptoms of sleep apnea in the FHS (located in MUC2 and SH3BP1)." (PMID 29093733, 2017). "Significant associations of symptoms of sleep apnea were observed with six rare variants [minor allele frequency (MAF) <1%] (located in ACE, AIFM3, LIPJ, MUC2, AP2A2, SH3BP1)." (PMID 29093733, 2017).
small intestinal carcinoma (1 paper, 2014). "We also previously examined mucin expression in small intestinal carcinoma, and found positive expression rates of MUC1, 51.7%; MUC2, 26.7%; MUC3, 55.0%; MUC4, 51.7%; MUC5AC, 33.3%; MUC6, 10.0%; and MUC16, 8.3% (MUC17 expression was not examined)." (PMID 25551773, 2014).
Trichinella spiralis infection (1 paper, 2022). "Production of MUC2 was significantly upregulated during Trichinella spiralis infection in mice, and experimentally infected pigs by Trichinella spiralis had increased mucins stored in goblet cells." (PMID 36676016, 2022).
Zinc deficiency (1 paper, 2020). A deficiency of the essential metal Zinc; an essential cofactor for many enzymes. "Synthesis and secretion of mucins were severely disturbed during zinc deficiency, affecting both MUC2 and MUC5AC mRNA expression with ongoing cell differentiation." (PMID 32858966, 2020).
tumor (247 papers, 1993 to 2026). "The suppression of MUC2 expression is found to be associated with IL-6 overexpression, which leads to inflammation and tumor growth." (PMID 40699805, 2025). "After 48 h of bromelain treatment, cellular MUC2 expression was greatly diminished, suggesting both a reduction in tumor cells and a loss in mucin production." (PMID 38704503, 2024). "Increased expression of MUC2 was associated with better OS in lower GI tumors adjusted for age, stage, tumor type (colon/appendix), and stratified by study site (HR 0.72; 0.55–0.95; P = 0.020)." (PMID 36222710, 2022). "MUC-2 gene deficiency of mice caused changes in biochemistry and molecular pathways; thereby the probability of tumor was facilitated." (PMID 35812452, 2022). "In the FUSCC cohort, MUC1 absence was associated with increased proportion of stage III PDAC (p = 0.011), and MUC1 absence and MUC2 presence were associated with tumour perineural aggression (p = 0.011 and p = 0.030, respectively)." (PMID 35910854, 2022). "While the presence of MUC2 is associated with an immunosuppressive environment, the tumor immune environment of mucinous CRC and the role of immune-mediated tumor cell death likewise require further investigation." (PMID 33808549, 2021). "Animal studies have suggested that the inactivation of the MUC2 gene causes tumor formation in the small intestine and then in the colon." (PMID 35572847, 2021). "MUC2 positive or GI-type SRC-GC was associated with larger tumour diameter, increased depth of invasion, presence of lymph-node metastases, or lymphovascular invasion." (PMID 32488651, 2020). "Considering that Muc2 is closely associated with tumours, can Amuc_1434 control the occurrence and development of tumours by degrading Muc2?" (PMID 31861919, 2019). "Our previous work established that Muc2 deficiency was linked to low chronic inflammation resulting in tumor development in the small, large intestine including the rectum." (PMID 29069719, 2017). "Expression of MUC2, which is secreted from goblet cells in the gut, has been associated with relatively indolent tumor growth." (PMID 25671432, 2015). "MUC2 has also been implicated in cancer metastasis previously through a tumor-associated macrophage (TAM)-dependent mechanism." (PMID 26555578, 2015). "Previous work have demonstrated that targeted gene knockout of the Muc2 gene caused tumor formation in entire gastrointestinal tract, including duodenum, colon and rectum, and the Muc2−/− mice are susceptible to DSS-induced inflammatory bowl diseases." (PMID 24941171, 2014). "Previous in vitro studies have indicated that MUC2 promotes cancer growth and metastasis through a tumor-associated macrophage (TAM)-dependent mechanism." (PMID 24324582, 2013). "MUC2 has been associated with less aggressive tumour phenotypes and improved survival in some studies, although reverse findings have also been reported." (PMID 21339979, 2010). "Mucin alterations are a common feature of esophageal neoplasia, and alterations in MUC2 mucin have been associated with tumor progression in the esophagus." (PMID 19014523, 2008). "While only a few tumour cells of PAC120 expressed MUC2, the HID variants contained much more cells staining positive for MUC2." (PMID 14760390, 2004). "Notably, many detached epithelial structures were located in the colonic sub-mucosa of VN-/- mice and in the MUC2+ cysts (yellow arrows), suggesting that Notch-1-deficient epithelial cells have acquired motility and tumor invasion properties." (PMID 30323897, 2018). "Muc2 deficiency not only accelerated the kinetics of tumor formation and increased tumor number initiated by loss of Apc function, but also shifted tumor location, with an increased tumor load in the colon." (PMID 29069719, 2017). "The regulatory role of MUC2 in tumor progression suggests that MUC2 could be considered as a new diagnostic marker for cancer diagnosis and a new drug target for the cancer therapy." (PMID 27835575, 2016).
tumor (continued). "Additionally, MUC2 expression was associated with mucinous differentiation and inversely correlated with lymphovascular invasion and tumor differentiation." (PMID 27298226, 2016). "Interestingly, partial loss of Muc2 contributed to the tumor development in APCMin mice in a fashion similar to APC-Cld-1 mice." (PMID 24997475, 2014). "An exception was cluster 3 (secretory progenitor cells), which according to immunohistochemical staining for Muc2 consists of Defa6-tdTom cells distributed throughout the tumor." (PMID 40221753, 2025). "CCFM683 inhibited the NF-κB signaling pathway, up-regulated MUC2, Claudin-1, and ZO-1, and promoted tumor cell apoptosis via the CLA-PPAR-γ axis." (PMID 39924893, 2025). "The increased MUC5 and decreased MUC2 expression in CRC is also associated with the increased prevalence of lymph node metastasis and advanced tumor stages." (PMID 40699805, 2025). "Cluster 10 showed elevated REG4 and MUC2, characteristic of a tumor-specific deep crypt secretory (tDCS) identity." (PMID 41282138, 2025). "Acting as a tumor suppressor, the MUC2 knockout mice models showed early development of GI tumor and invasion of carcinoma, along with a reduced number of goblet cells, decreased apoptosis, and the increased migration of intestinal epithelial cells." (PMID 40699805, 2025). "Mechanistically, the samples suppressed tumor growth via apoptosis regulation; restored epithelial integrity by modulating MUC-2, MUC-3, and TFF-3 expression; and attenuated inflammatory cytokine expression through NF-κB pathway modulation." (PMID 41154100, 2025). "These cell lines provided an ideal platform to assess the impact of MUC2 modulation on immune cell infiltration into the tumor and its interplay with immune cells in a controlled and reproducible in vitro setting." (PMID 39926604, 2024). "Compared with normal group, the expression of occluding, claudin-1, ZO-1 and Muc2 in tumor model group were prominently reduced, but they were all restored after the intervention of XRZYBXD." (PMID 40046008, 2024). "Biomarkers of intestinal differentiation β-catenin and mucin 2 (MUC2) were inversely regulated, with the former upregulated in adenocarcinoma tissue and positively correlated with tumor marker CA19-9." (PMID 39337548, 2024). "By delving deeper into the characterization of GC cells, we identified 6 specific tumour cell subtypes: C0 PSCA+ tumour cells, C1 CLDN7+ tumour cells, C2 UBE2C+ tumour cells, C3 MUC6+ tumour cells, C4 CHGA+ tumour cells and C5 MUC2+ tumour cells." (PMID 38894657, 2024). "These alterations in MUC2 expression and glycosylation contribute to disrupted mucin barrier function and promote tumor cell invasion and metastasis." (PMID 39682117, 2024). "By employing CRISPR-mediated MUC2 knockout, we investigated the influence of MUC2 on tumor immune infiltration and its interplay with T cells and NK cells enriched peripheral blood mononuclear cells (PBMCs) in 3D spheroid cultures." (PMID 39926604, 2024). "Liver metastases made from POU5F1high-med cells produced cells positive for the differentiation markers, CK20 and MUC2, and produced mucus, recapitulating tumor differentiation." (PMID 37996567, 2023). "Abnormal glycosylation leads to the changes in the structure of tumor-associated mucins, including MUC1 and MUC2, contributing to metastasis formation." (PMID 35936008, 2022). "The secretion of MUC2 forms an insoluble mucous gel barrier, which is usually identified as a tumour suppressor." (PMID 35910854, 2022). "The expression of genes encoding mucins (MUC1, MUC2 and MUC5A) or involved in mucosa protection (TFF1 and TFF3) were positively correlated with AGR2 expression in most tumour types." (PMID 35857928, 2022).